EFEMP1 (EGF-like fibulin extracellular matrix protein 1)
Diseases named in the same sentence as EFEMP1 in open-access papers (continued):
Sharing a sentence is not in itself a finding about the gene and the disease.
tumor (continued). "EFEMP1 has also been reported to activate Notch signaling in vitro, although with less efficiency than JAG1, and to exert both tumor suppressive and oncogenic effects in various cancers by participating in multiple signaling pathways." (PMID 30102696, 2018). "Based on functional assays on tumor suppression activities, a protein modified from wild-type EFEMP1 was obtained, which we have named ESTP (EFEMP1- derived tumor suppressor protein)." (PMID 27713911, 2016). "In addition to its dual functions in the two key cell subpopulations in tumor formation, the effect of EFEMP1 on maintaining a relatively stable subpopulation equilibrium may include its role in suppressing mis-segregation of Chr7, which drives diversification of cell subpopulations." (PMID 26307682, 2015). "Over-expression of EFEMP1 eliminated tumor development and suppressed angiogenesis, cell proliferation, and VEGFA expression, while the converse was true with knock-down of endogenous EFEMP1 expression." (PMID 21955618, 2011). "However, EFEMP1 and TP63 were expressed at low levels in tumor tissues and at high levels in normal tissues." (PMID 37441420, 2023). "Even though a slight decrease in fibulin-3 levels was observed also in some of the tumor nodules in the MDA-MB-468 + NFs miR-9 group, no modulation of EFEMP1/fibulin-3 expression was detected in MDA-MB-468 cells overexpressing miR-9 in in vitro experiments." (PMID 32972039, 2020). "The correlation between gender, age, tumor position, tumor size, histologic type, and serum EFEMP1 levels in OS patients is not statistically significant (P > 0.05)." (PMID 32280689, 2020). "In our study, the diagnostic methylation of cg05385513, which is located at the promoter region of EFEMP1, had higher methylation level in tumor than that in the normal tissues." (PMID 28938548, 2017). "Furthermore, our results showed that EFEMP1 suppressed EMT through blocking the Wnt/β-catenin signaling, which further inhibited tumor invasion and migration in EC." (PMID 27015552, 2016). "We dissected EFEMP1 to identify domains responsible for its cell context-dependent dual functions, with the goal being to construct an EFEMP1-derived tumor-suppressor protein (ETSP) that lacked tumor-promoting function." (PMID 27713911, 2016). "Together with our previous results, we speculated that EFEMP1 is a downstream target molecule of AEG-1, mediating the tumor migration and invasion." (PMID 25987128, 2015). "The data obtained in this study verified the effect of EFEMP1 in suppressing EGFR-driven cancer cell growth, and demonstrated a new activity of EFEMP1 in suppressing cell type/proportion change within a tumor, thereby maintaining existing intra-tumoral heterogeneity." (PMID 26307682, 2015). "It was postulated that EFEMP1 can serve as a target that restricts anti-invasive and chemosensitizing effects to tumor cells without the pleiotropic effects of current pharmacologic inhibitors of Notch." (PMID 24495907, 2014). "This is consistent with the lack of an EFEMP1-mediated effect on cell proliferation in serum-containing culture medium, in contrast to the dramatic suppression of tumor formation in both s.c. and i.c. xenograft systems." (PMID 21955618, 2011). "Finally, EGF‐containing fibulin‐like extracellular matrix protein 1 (EFEMP1), which binds to epidermal growth factor receptor (EGFR) to promote tumor growth, invasion, and metastasis, showed a threefold increase across seven O‐linked glycosylation sites in tumor tissue." (PMID 30459171, 2018). "In contrast, there is little evidence for the pro-tumor effects of EFEMP1." (PMID 25987128, 2015). "Therefore, we speculate that EFEMP1 is a downstream target molecule of AEG-1, and EFEMP1 mediates its effects on tumor migration and invasion." (PMID 25987128, 2015).
tumor (continued). "Indeed, considering all tumour and non-cancerous tissue samples tested, only 10 out of 356 would be misclassified according to the EFEMP1 methylation test: eight PCa would not be detected and only 1 BCa and 1 RCT would be misdiagnosed as PCa." (PMID 25211630, 2014). "In contrast, EFEMP1 was under-expressed (less than half of the average of the normal cortex tissues) in 40% and overexpressed (more than 2-fold of the normal cortex tissues) in 19% of all tumors, without any significant correlation with tumor grade." (PMID 25594013, 2014). "Furthermore EFEMP1 was found to strongly interact with other extracellular matrix (ECM) proteins such as TIMP3, and blocked the functional activity of VEGF, and inhibited tumor metastasis." (PMID 23840707, 2013). "Interestingly, subpopulation equilibria in xenografts of U251-NS without EFEMP1 overexpression were responsive to inoculum size (1, 10 and 100 thousand cells), which may change the tumor-onset environment." (PMID 26307682, 2015). "Remarkably, no EFEMP1 promoter methylation was found in the vast majority of tested BCa and RCT samples, emphasizing the tumour specificity of this methylation assay." (PMID 25211630, 2014).
cancer (70 papers, 2011 to 2026). A tumor composed of atypical neoplastic, often pleomorphic cells that invade other tissues. "Two additional upregulated hubs supported regenerative processes: CTGF, a central mediator of tissue remodeling and EFEMP1 promoter of cell growth often implicated in cancer." (PMID 31829262, 2019). "However, further studies using larger sample sizes are required to confirm these results and understand the underlying mechanisms of EFEMP1 in cancer progression and patient outcomes." (PMID 38031171, 2023). "Regarding disease and functions, we recognized that EFEMP1 may be associated with cell movement, angiogenesis and cancers in the enrichment analyses." (PMID 34204134, 2021). "Furthermore, EFEMP1 expression changes are implicated in the progression of numerous types of cancer, an area in which fibulin-3 has putative significance as a therapeutic target." (PMID 32911658, 2020). "Specifically, EFEMP1 exhibits diverse expression patterns across different tissues and exerts a dual function in cancer progression." (PMID 39822989, 2025). "The expression of MISP, CHMP2B, IL-18, TMSB4X, and EFEMP1 proteins in carcinoma tissue was higher than that in para-carcinoma tissues." (PMID 38835670, 2024). "Our data demonstrated that EFEMP1 expression was an independent prognostic factor for cancer death and metastasis in UTUC and UBUC." (PMID 34204134, 2021). "As an important regulator in the extracellular matrix, including cell-to-cell and cell-to-matrix communication, EFEMP1 has been investigated in carcinogenesis.The deregulation of EFEMP1 in cancer development is complex." (PMID 34204134, 2021). "We discovered that epidermal growth factor-containing fibulin-like extracellular matrix protein 1 (EFEMP1) was the most upregulated gene, which was significantly related to advanced UC stage and disease metastasis, suggesting its role in cancer progression." (PMID 34204134, 2021). "In UTUC, high EFEMP1 expression levels contributed to higher rates of cancer-related deaths (27.1% vs. 8.8%) and postoperative cancer metastasis (31.2% vs.10.0%) than low EFEMP1 expression levels." (PMID 34204134, 2021). "EFEMP1 is an important extracellular protein employed in cancer evolution via differential regulation of gene expression in different populations to achieve cell-context dependent dual function." (PMID 32580319, 2020). "Combined, these studies suggest that EFEMP1 plays different roles in the development of different types of carcinoma." (PMID 32555395, 2020). "Epidermal growth factor‐containing fibulin‐like extracellular matrix protein 1(EFEMP1) has been found to be involved in the occurrence and development of many cancers." (PMID 30972979, 2019). "The expression levels of Caspase‐3, Caspase‐8, Caspase‐9, and PARP in cancer cells overexpressing EFEMP1 were detected by Western blotting." (PMID 30972979, 2019). "Previous studies have revealed that EFEMP1 played a role in the nature of many malignant tumors and interacted with its partners." (PMID 28380465, 2017). "EGF-containing fibulin-like extracellular matrix protein (EFEMP1) (also fibulin-3) has the multiple functions of suppressing cancer growth and angiogenesis, while promoting cancer cell invasion." (PMID 29290950, 2017). "The EGF-containing fibulin-like extracellular matrix protein 1 (EFEMP1), an extracellular matrix (ECM) protein, is associated with the tumorigenesis in different types of carcinoma." (PMID 28938548, 2017). "Taken together, these data suggest that HIF2α mediates hypoxia-induced cancer growth/metastasis and that EFEMP1 is a downstream effector of hypoxia-induced HIF2α during breast tumorigenesis." (PMID 27270657, 2016). "Inversely, in sporadic breast cancer and non-small cell lung cancer, EFEMP1 was reported to be silenced through hypermethylation of the promoter region and suppress cancer invasion." (PMID 27015552, 2016).
cancer (continued). "Previous researches have showed that EFEMP1 was correlated with the tumorigenicity of a variety of carcinomas." (PMID 27351229, 2016). "All together, these suggest that in the STIC context, EFEMP1 has a cancer stem cell transforming effect via enhancing both oxidative phosphorylation and aerobic glycolysis, which is consistent with the NOTCH1 up-regulation." (PMID 26307682, 2015). "Expression analysis of EFEMP1 and characterization of histone marks were performed in tissue samples and cancer cell lines to determine the impact of epigenetic mechanisms on EFEMP1 transcriptional regulation." (PMID 25211630, 2014). "EFEMP-1 is another important cancer-related gene that was differentially expressed in UV-treated J cybrids." (PMID 24919117, 2014). "In our system, EFEMP1 expression was up-regulated in TIMP-2 overexpressing cells, rendering a 6.507 decrease fold-change in cancer development and metastasis-associated functions." (PMID 26056585, 2014). "Consistent with its role as an extracellular matrix protein, EFEMP1's function in cancer was demonstrated to be an effect in the extracellular compartment, by using a purified human recombinant EFEMP1 protein." (PMID 25594013, 2014). "The anti-cancer properties of EFEMP1 were initially thought to be derived from direct targeting of endothelial cell proliferation to suppress angiogenesis in cancer." (PMID 25594013, 2014). "Efemp1 mRNA expression was variable increased ranging from 1.5 to over 10 fold induction in cancers compared to normal tissues." (PMID 23470560, 2013). "In particular, we have shown metastatic suppression of EFEMP1 and its association with EMT, which is the first mention in cancer." (PMID 23840707, 2013). "Further investigation is needed to understand the molecular context of EFEMP1 in control of different malignant behaviors of cancer cells." (PMID 21955618, 2011). "Second, MFAP4 and EFEMP1 have been well studied in various cancers, and the intricate mechanisms underlying the upregulation of MFAP4 and EFEMP1 in platinum-resistant OC patients remain unclear, necessitating further exploration in future research." (PMID 39822989, 2025). "However, in the breast, prostate, lung, colorectal and liver cancers, EFEMP1 is downregulated in cancer tissues." (PMID 34204134, 2021). "Finally, there are conflicting reports regarding the function of EGF-containing fibulin-like extracellular matrix protein 1 (EFEMP1) in diverse cancer types." (PMID 34069906, 2021). "Moreover, patients with high EFEMP1 expression increased the risks of UC-related cancer death and metastatic development in UTUC and UBUC." (PMID 34204134, 2021). "Through previous studies, we found that EFEMP1 was involved in the regulation of many biological processes in carcinoma, suggesting that EFEMP1 may play an important role in the development of HCC." (PMID 30972979, 2019). "Our finding that BBOX1 and EFEMP1 were suppressed by cancer exosomes may indicate activation of a protective mechanism in the recipient cells against potentially harmful cargos in cancer exosomes." (PMID 30008265, 2018). "Overall, the data suggest a role of EFEMP1 in checking cancer plasticity, which is hypothesized to be related to its cell-subpopulation context-dependent dual function." (PMID 26307682, 2015). "Conflicting functions of EFEMP1 in cancer have been reported." (PMID 26307682, 2015). "EFEMP1's transforming and pro-invasive functions may play a key role in cervical and ovarian carcinoma, where EFEMP1 expression was correlated with poor prognosis." (PMID 26307682, 2015). "Within specific cancer cell contexts, EFEMP1 may promote or suppress cell growth, by enhancing or reducing AKT phosphorylation, respectively." (PMID 25594013, 2014). "In PDAC, Efemp1 mRNA was upregulated in 13 of 15 investigated cancer specimens." (PMID 23470560, 2013). "There are conflicting reports regarding the function of EFEMP1 in different cancer types." (PMID 21955618, 2011).
cancer (continued). "However, an opposite effect of EFEMP1 in cancer has also been observed." (PMID 40316017, 2025). "Furthermore, multivariate Cox regression analysis revealed that EFEMP1 expression was an independent predictor of cancer-related death (p = 0.014; hazard ratio [HR], 2.233; 95% confidence interval [CI], 1.179–4.230) and metastasis occurrence (p =0.005; HR,1.21; 95% CI, 1.204–2.756)." (PMID 34204134, 2021). "EFEMP1, also known as fibulin 3, may have a potential cancer-promoting function in BC." (PMID 33182810, 2020). "In addition, extensive EFEMP1 methylation was particularly present in malignant tumors without GNAS mutations and associated with disease-free survival of patients with IPMNs (p < 0.0001)." (PMID 27095449, 2016). "However, the role of EFEMP1 in tumorigenesis and cancer progression remains controversial." (PMID 27015552, 2016). "In reviewing published studies on EFEMP1 in cancer and incorporating results from this study, it should be noted that EFEMP1's function, whether promoting or inhibiting cancer growth, may be dependent on a molecular context that differs by cancer cell type and malignancy stage." (PMID 21955618, 2011). "As previously reported, EFEMP1 reduced the expression of MMP2 and MMP9 by regulating the activity of ERK1/2, thereby inhibiting the migration of cancer cells." (PMID 40316017, 2025). "Concerning CAV1, EFEMP1, FBLN2, TGFBI, or VDAC1, their actions are highly context-dependent and can vary across different cancer types and stages." (PMID 39201614, 2024). "Compared with paracancerous tissues, AKAP7, EFEMP1, EPN2 and LAMA2 were lowly expressed in cancer tissues, while RPS6KA1, SLC1A6, TRABD and ZNRD1 were highly expressed in cancer tissues." (PMID 37123010, 2023). "In this study, EFEMP1, LAMA2 and SLC1A6 were differentially expressed not only in N0 and N1–N3 groups, but also in cancer and paracancerous groups." (PMID 37123010, 2023). "The urine proteome profile of PCa and cancer-free subjects was analyzed by two software packages and 18 dysregulated proteins, of which 5 (TTR, EFEMP1, CDH1, SECTM1, KLK3) common to both software, were found." (PMID 35454907, 2022). "Upon further dose- and time-dependent exosome transfection experiments validation by qRT-PCR, we found that cancer exosomes induced stronger upregulation of MMP9 and PGAM1 whilst suppressed BBOX1 and EFEMP1, compared to normal exosomes." (PMID 30008265, 2018). "EFEMP1-derived tumor suppressor protein (ETSP) retains EFEMP1’s anti-growth and anti-angiogenic functions while actually inhibiting cancer cell invasion." (PMID 29290950, 2017). "Overexpression of EFEMP1 nearly abolished intracranial tumorigenicity of TMC-enriched U251, however, EFEMP1 overexpression in STIC-enriched U251-NS promoted cancer stem cell features." (PMID 27713911, 2016). "EFEMP1, a kind of extracellular matrix (ECM) protein, has been suggested to correlate with the development of different types of carcinoma." (PMID 27351229, 2016). "The results showed that there was lower mRNA level of EFEMP1 in 18(60%) of the cancer tissues compared with adjacent noncancerous tissues, and the difference was statistically significant." (PMID 30972979, 2019). "Conversely, cancer exosomes triggered dose-dependent inhibition of BBOX1 and EFEMP1." (PMID 30008265, 2018). "We speculated that the relationship between EFEMP1 and EMT may be determined by the role of EFEMP1 in different cancers." (PMID 27351229, 2016). "We observed positive expression of EFEMP1 in 19.1% (16/84) of carcinomas, which was significantly lower than that seen in 80% of normal endometrium (32/40) and 70% of atypical hyperplasia (7/10) respectively (P<0.001 and P = 0.02, Table S1and S2)." (PMID 23840707, 2013). "Indeed, restoring EFEMP1 levels was found to improve mitotic fidelity, suggesting that modulating the ECM by restoring EFEMP1 levels might reduce CIN rates in cancer." (PMID 38067140, 2023).
cancer (continued). "Furthermore, high EFEMP1 expression also predicted UBUC metastasis and cancer-related deaths." (PMID 34204134, 2021). "Even though the mechanisms by which EFEMP-1 might contribute to AMD is not known, based upon the cancer studies, it is reasonable to speculate that numerous downstream pathways are activated by increased EFEMP-1 levels." (PMID 24919117, 2014). "Interestingly, cancer exosomes, but not normal exosomes, modulated expression of matrix remodelling (EFEMP1, DDK3, SPARC), cell cycle (EEF2K), membrane remodelling (LAMP2, SRPX), differentiation (SPRR2E), apoptosis (CTSC), transcription/translation (KLF6, PUS7)." (PMID 30008265, 2018).
connective tissue diseases (3 papers, 2021 to 2024). "Among the non-collagenous ECM proteins, EFEMP1/FIBULIN3 has been shown in humans and mice to be expressed in a wide range of tissues, including cartilage and bone, and to be involved in numerous connective tissue diseases." (PMID 38200805, 2023).
infection (2 papers, 2020 to 2025). The state of being infected such as from the introduction of a foreign agent such as serum, vaccine, antigenic substance or organism. "EFEMP1 and LTBP4 were additionally downregulated at 12 hpi and 24 hpi following Delta infection, while EGFL6 and FBLN5 showed consistent downregulation at both time points in Omicron infection." (PMID 41200555, 2025).
eye disorder (1 paper, 2020). A non-neoplastic or neoplastic disorder that affects the eye. "Thus, the iPSC lines we have developed could be very useful for screening small molecule modulators of EFEMP1 and other eye-related DEGs for a wide range of eye disorders." (PMID 32393163, 2020).
EFEMP1 also shares sentences with these, for which no sentence is quoted: malignant pleural mesothelioma (6 papers); colorectal cancer (4); Sorsby fundus dystrophy (4); brain tumors (3); carpal tunnel syndrome (3); heart disease (3); abdominal hernia (2); adenoma (2); Cirrhosis (2); diabetes (2); emphysema (2); epithelioid mesothelioma (2); hemorrhoid (2); ischemic stroke (2); kidney (2); lung adenocarcinoma (2); nonalcoholic fatty liver disease (2); retinitis pigmentosa (2); urothelial carcinoma (2); Abdominal obesity (1); acute myeloid leukemia (1); Alzheimer disease (1); amyotrophic lateral sclerosis (1); asbestosis (1); asthma (1); autosomal recessive polycystic kidney disease (1); autosomal recessive retinitis pigmentosa (1); cervical tumors (1); childhood glaucoma (1); cholestasis (1).
A further 48 diseases each share a sentence with EFEMP1 in 1 paper.